TFF1 (trefoil factor 1)
Diseases named in the same sentence as TFF1 in open-access papers (continued):
Sharing a sentence is not in itself a finding about the gene and the disease.
breast carcinoma (continued). "The combined measurement of both TFF1 and TFF3 mRNA level for differentiation of metastatic from nonmetastatic breast cancer gave 57.69% sensitivity and 83.3% specificity." (PMID 29977293, 2018). "Serum concentrations of TFF1 and TFF3 but not TFF2 are higher in women with breast cancer than in women without breast cancer." (PMID 28687783, 2017). "Immunohistochemically, TFF1 expression was positive in 56.5% and TFF3 was positive in 73.9% of breast cancers, while TFF2 was negative in all tumors." (PMID 28687783, 2017). "For example, the absence of TFF1 enhances the tumorigenic abilities of MCF7, a breast cancer cell line, in vitro and in vivo." (PMID 29296124, 2017). "TFF1 and TFF3 mRNAs were induced by oestrogen in five oestrogen-responsive but not in two oestrogen-nonresponsive breast cancer cell lines." (PMID 25900183, 2015). "Expression microarray analysis, which demonstrated consistent regulation of TFF1 and TFF3 but not TFF2 in three oestrogen-responsive breast cancer cell lines, was validated by real-time RT-PCR." (PMID 25900183, 2015). "We found BPAF stimulated the endogenous transcription of TFF1, GREB1 and CTSD genes through both dose and time-dependent manners in ERα-positive T47D and MCF7 human breast cancer cells, but not in ERα-negative MDA-MB-231 cells." (PMID 24727858, 2014). "TFF1 and TFF3 are expressed in both breast cancer tissue and normal breast." (PMID 28687783, 2017). "However, there was no co-relation between TFF1, TFF2, and TFF3 expression and ER in breast cancer tissue in this patients’ series." (PMID 28687783, 2017). "To address whether the induction of TFF1 by TOX3 was ER-dependent, we transfected triple negative basal MDA-MB-231 breast cancer cells, which do not express ER or TOX3." (PMID 25632947, 2015). "To evaluate the effect of BPAF on endogenous transcription, we conducted the real-time PCR to detect mRNA levels of estrogen responsive genes, such as TFF1, GREB1 and CTSD in ERα-positive T47D and MCF7 breast cancer cell lines and ERα-negative MDA-MB-231 breast cancer cell line." (PMID 24727858, 2014).
gastric cancer (77 papers, 2009 to 2026). A primary or metastatic malignant neoplasm involving the stomach. "Functional validation confirmed that TFF1 was associated with increased gastric cancer cell migration." (PMID 42193868, 2026). "More recently, several reports revealed that TFF1 functions as a tumor suppressor in the gastrointestinal epithelium such that TFF1 deficiency is associated with the development and progression of gastric cancer and Barrett’s esophageal cancer." (PMID 40940735, 2025). "In line with this notion, TFF1-deficient mice serve as a popular model for gastric cancer development." (PMID 39410561, 2024). "We found an association between reduced expression of TFF1 and the development and progression of gastric cancer in dogs." (PMID 34679875, 2021). "Of note, somatic mutations in the TFF1 gene seem to be associated with gastric cancer and there is a strikingly reduced TFF1 expression in the majority of gastric carcinomas." (PMID 32630599, 2020). "Taken together, Tff1 represents a gastric tumor suppressor gene in mice and TFF1 mutations and dysregulated TFF1 expression seem to be critical to the pathogenesis of most gastric carcinomas in humans." (PMID 32630599, 2020). "Loss of TFF1 is a frequent finding in human gastric cancer that occurs via a number of molecular alterations such as LOH18, promoter methylation, and transcription suppression." (PMID 31292446, 2019). "Suppression of GATA6 in gastric cancer is associated with poor prognosis and likely promotes tumorigenesis by reducing the expression of trefoil factor 1 (TFF1) and trefoil factor 2 (TFF2)." (PMID 29720137, 2018). "In gastric cancer, the loss of TFF1 can contribute to the induction of pro-inflammatory and anti-apoptotic genes through activation of NF-κB pathway." (PMID 29296124, 2017). "The transcription factor C/EBPβ is frequently overexpressed in gastric cancer and associated with the suppression of the differentiation marker TFF1." (PMID 27522676, 2016). "Of note, approximately two-thirds of human gastric cancers, where H. pylori is a risk factor, demonstrate downregulation of TFF1 expression." (PMID 25980439, 2015). "Trefoil factor 1 (TFF1) was expressed in normal gastric mucosa, but frequently downregulated in gastric cancers because of gene mutation and promoter hypermethylation." (PMID 26417932, 2015). "Several studies confirm that tff1 expression is frequently lost in gastric cancer because of deletions, mutations or methylation of the tff1 promoter." (PMID 24236136, 2013). "Tff1 acts as a tumor suppressor gene and its deficiency results in spontaneous gastric cancer in mice." (PMID 23217022, 2012). "TFF1, which encodes trefoil factor 1, is suggested to be a tumor suppressor gene that is lost or methylated in many gastric cancers." (PMID 21194482, 2010). "Missense mutations in TFF1 have been found in gastric cancers however their importance is uncertain." (PMID 18722547, 2009). "We also show frequent loss of TFF1 with nuclear localization of STAT3 in human gastric cancers." (PMID 31292446, 2019). "In addition, a study in gastric cancer showed that the loss of TFF1 is associated with the activation of NF-κB." (PMID 31455213, 2019). "Indeed, more than 50% of gastric cancers show a reduced TFF1 expression due to some point mutations, promoter polymorphic variants, but mostly to loss of heterozygosity (LOH) and hypermethylation of its promoter." (PMID 29085807, 2017). "Loss of TFF1 expression occurs frequently in human gastric cancer." (PMID 18722547, 2009).
gastric cancer (continued). "In any case, we show that in gastric cancer development, high expression of C/EBPβ leads to reduction of RUNX1t1 expression and loss of RUNX1t1 may support unrestrained C/EBPβ function and repression of differentiation genes, including TFF1." (PMID 27522676, 2016). "Research has found that ER-γ protects gastric cells from H. pylori infection and inhibits gastric cancer cell growth by regulating TFF1 and NF-κB." (PMID 40364840, 2025). "Tff1 is specifically expressed in gastric surface epithelial cells and is frequently lost in human gastric cancer through genetic alterations or promoter hypermethylation, making this model highly relevant to human disease." (PMID 40673273, 2025). "In our study, we observed that TFF1 expression was downregulated in gastric cancer-derived KATO III cells upon exposure to IFNγ alone, whereas in primary human gastric mucosoids, its repression required a combination of TNF-α, IL-1β, and IFNγ." (PMID 41573568, 2025). "In our previous work, we identified C/EBPβ as an IFNγ-responsive gene in KATO III gastric cancer cells and demonstrated that IFNγ stimulation enhances its recruitment to the TFF1 promoter, leading to gene downregulation." (PMID 41573568, 2025). "In gastric cancer, ER-γ binds to the Trefoil factor 1(TFF1) promoter and induces TFF1 gene expression." (PMID 40364840, 2025). "TFF1 is specifically expressed in gastric surface epithelial cells and is frequently lost in human gastric cancer, making this an appropriate cellular target for modeling gastric tumorigenesis." (PMID 40673273, 2025). "In gastric cancer, miR-423-5p is up-regulated and targets TFF1, affecting gastric cancer cell proliferation and invasion." (PMID 39677943, 2024). "Because the TFF1 expression in normal tissue strongly predominates in stomach mucosa, TFF1 immunohistochemistry (IHC) has been suggested as a marker for gastric cancer." (PMID 39410561, 2024). "Five proteins were associated with the risk of stomach cancer including ANXA10 and TFF1 [1.75 (1.51–2.02) and 1.90 (1.58–2.28)]." (PMID 38750076, 2024). "In gastric cancer, miR-423 has been reported to enhance cell proliferation and invasive potential by targeting the tumor suppressor gene TFF1 (trefoil factor family 1)." (PMID 37568586, 2023). "In human gastric cancer, it is widely accepted that TFF1 is markedly low-expressed and functions as a gastric tumor suppressor." (PMID 36755810, 2023). "Then, we evaluated the relationship between the TFF1 expression and prognosis in gastric cancer cohort." (PMID 36428568, 2022). "In order to discover the function of TFF1 MS and TFF2 MS in gastric cancer, wild-type (WT) and mutation-type (MUT) plasmids were constructed." (PMID 36428568, 2022). "In this study, we first identified that TFF1/TFF2 expressions were mediated by DNA methylation in gastric cancer." (PMID 36428568, 2022). "Our results also agree with a study that demonstrated a progressive decrease in TFF1 and an increase in NF-κB activation during gastric cancer development." (PMID 36139637, 2022). "Followed by the mutation of TFF1 MS and TFF2 MS, the protein and mRNA expression were reverted in two gastric cancer cell lines." (PMID 36428568, 2022). "Visualized by UCSC-XENA, we found out that the lower expression of TFF1 predicted the better overall survival status of the gastric cancer patients." (PMID 36428568, 2022). "Our results revealed that the protein expression of TFF1 was also suppressed in gastric cancer specimens." (PMID 36428568, 2022). "Such a nuclear localization was also observed in MKN28 gastric cancer cells, and this nuclear localization was significantly reduced by treatment with a TFF1-conditioned medium." (PMID 35628183, 2022). "It was observed that the gastric cancer tissues presented lower TFF1 and TFF2 expressions than normal tissues, and their mRNA expression was negatively related to the DNA methylation level." (PMID 36428568, 2022).
gastric cancer (continued). "When RUNX1T1 combines with C/EBPβ, its binding with DNA and repression of the TFF1 promoter gene are significantly interrupted, which reduces the proliferation of gastric cancer cell lines and slows oncogenesis." (PMID 35902872, 2022). "TFF1 expression is markedly reduced in human GCs, suggesting that TFF1 is a tumor suppressor for human gastric cancer." (PMID 34679875, 2021). "First, we used AGS human gastric cancer cell lines expressing TFF1 or empty-vector pcDNA as a control (CTRL)." (PMID 34419066, 2021). "In recent years, clinical and experimental studies have shown an active function of the TFF1 in the oncogenic transformation, growth, and metastatic extension of common human solid tumors, including breast, pancreas, colon, and stomach cancer." (PMID 34679875, 2021). "Downregulation of both Tff1 and Tff2 expression also frequently occurs in gastric cancers displaying tumor suppressor function." (PMID 32231118, 2020). "We also identified three LSL-hMYH9; Atp4b-cre; Tff1-/- mice with advanced gastric cancer, suggesting that hMYH9 promoted GC progression." (PMID 32685004, 2020). "The reconstitution of TFF1 protein in human gastric cancer cells and 3D gastric glands organoids from TFF1-KO mice abrogates IL6-induced nuclear p-STAT3Y705 expression." (PMID 31292446, 2019). "To investigate if the oxidative stress-induced anti-proliferative and pro-apoptotic effects of GKN2 in gastric cancer cell were TFF1-dependent, we overexpressed or knocked down TFF1 in GKN2-overexpressing and control cells." (PMID 31382983, 2019). "The TFF1 protein expression levels in gastric cancer were significantly lower than normal gastric tissues (P < 0.001)." (PMID 31292446, 2019). "Inhibition of AURKA also reduced growth of xenograft tumors from human gastric cancer cells in mice and reversed the development of gastric tumors in Tff1-/- knockout mice." (PMID 28350359, 2017). "The reconstitution of TFF1 expression in gastric cancer cells suppressed H. pylori mediated NF-κB activation and expression of cytokine genes (TNF, IL-1β, CCL5, and IL-4 receptor)." (PMID 28350359, 2017). "Lack of TFF1 expression was correlated with high promoter methylation levels in patients with gastric cancer, and in vitro analyses also demonstrated that gastric cancer cells exposed to demethylating agents show increased levels of TFF1 expression." (PMID 29296124, 2017). "All normal gastric tissues express TFF1, but Im and co-workers have been shown to reduce the expression of this gene in gastric cancer." (PMID 28512631, 2017). "A tumor suppressor gene whose expression is frequently deregulated in gastric cancer by hypermethylation of the Trefoil factor 1 gene (TFF1) whose function is to defend and repair of gastrointestinal mucosa." (PMID 28512631, 2017). "In the current study, we observed a positive correlation between the expression of GATA6 and TFF1/2 in patients with gastric cancer and in gastric cancer cell lines." (PMID 27598141, 2016). "Given that GATA6 is a transcription factor of the gastroprotective trefoil genes TFF1/2, we therefore examined the expression of TFF1/2 in gastric cancer cell lines." (PMID 27598141, 2016). "A clinically significant correlation was also observed between the expression of GATA6 and TFF1/2 among tissue samples from 60 gastric cancer patients." (PMID 27598141, 2016). "In gastric cancer, it is possible that C/EBPβ activation represents an upstream event with broader implications to tumorigenesis, of which TFF1 down-regulation and COX2 overexpression are hallmarks." (PMID 27522676, 2016).
gastric cancer (continued). "The data also show that C/EBPβ is mandatory for the tumorigenic potential of gastric cancer cell lines by promoting cell proliferation and confirm the repressive effect of C/EBPβ on the expression of TFF1." (PMID 27522676, 2016). "Among the known common molecular changes in intestinal-type gastric cancer are enhanced expression of cyclooxygenase-2 (COX2) and diminished expression of the mucous-associated protein trefoil factor 1 (TFF1)." (PMID 27522676, 2016). "A significantly positive correlation was observed between the expression of GATA6 and TFF1/2 in the full set of patients with gastric cancer (n = 60)." (PMID 27598141, 2016). "The RUNX1t1 promoter was frequently hypermethylated and ectopic expression of RUNX1t1 in gastric cancer cells inhibited proliferation and enhanced TFF1 expression." (PMID 27522676, 2016). "Ectopic expression of RUNX1t1 reduced proliferation in gastric cancer cell lines and counteracted the repression of TFF1 by C/EBPβ." (PMID 27522676, 2016). "In N-methyl-N-nitrosourea (MNU)-induced gastric cancers, TFF1 methylation was increased after H. pylori infection." (PMID 26417932, 2015). "Collectively, these data clearly indicate that loss of Tff1 in addition to H. pylori infection increase the activation and nuclear localization of β-catenin in our Tff1-KO gastric cancer mouse model." (PMID 25980439, 2015). "Together, the immunofluorescence and reporter assays data clearly indicated that TFF1 expression decreases H. pylori-mediated β-catenin nuclear localization and transcriptional activation in gastric cancer cells." (PMID 25980439, 2015). "Our data demonstrated that the reconstitution of TFF1 expression in gastric cancer cells abrogated H. pylori-induced activation of β-catenin and decreased mRNA and protein expression of c-myc and cyclin D1." (PMID 25980439, 2015). "An example is the tumour suppressive function of TFF1, which has been proven in an animal gastric cancer model." (PMID 26390128, 2015). "A large study of approximately 300 gastric cancers has shown that TFF1 expression is significantly more reduced in cases with differentiated type and intestinal type gastric cancer." (PMID 25980439, 2015). "A reconstitution of TFF1 expression in gastric cancer cells decreased H. pylori-induced β-catenin nuclear translocation, as compared to control (p < 0.001)." (PMID 25980439, 2015). "In this study, we investigated the tumor suppressor function of TFF1, and added additional clues concerning the role of TFF1 in gastric cancer." (PMID 25015107, 2014). "In this study, we demonstrate, using colony formation assay and Annexin V staining, that reconstitution of TFF1 expression in gastric cancer cell models suppresses cell growth and promotes cell death." (PMID 25015107, 2014). "In our initial functional studies, we found that the reconstitution of TFF1 expression in gastric cancer cell models significantly decreased growth, indicating the tumor suppressor function of TFF1." (PMID 25015107, 2014). "AGS and STKM2 gastric cancer cell lines were transiently transfected with PG13-Luc or mutant PG13-Luc along with TFF1 or PTT5 empty vector for 48 hours." (PMID 25015107, 2014). "Using a Tff1 knockout mouse model, we and others have provided evidence supporting the tumor suppressor function of TFF1 and its anti-inflammatory role in gastric cancer." (PMID 25015107, 2014).